MTOR (mechanistic target of rapamycin kinase)
Diseases named in the same sentence as MTOR in open-access papers (continued):
Sharing a sentence is not in itself a finding about the gene and the disease.
tuberous sclerosis (continued). "PTEN mutations are associated with autism, as are tuberose sclerosis and fragile X, which disrupt mTOR signaling." (PMID 21347362, 2011). "Tuberous sclerosis mutations activate mammalian target of rapamycin (mTOR) and biochemically resemble VHL alterations." (PMID 15956968, 2005). "Similarly, everolimus, with a half-life of 25-35 hours, has shown success in treating seizures associated with tuberous sclerosis complex by inhibiting the mTOR signaling pathway." (PMID 39865817, 2025). "Tuberous sclerosis (TSC) is categorized among cortical development malformations arising from mutations in either TSC1 (hamartin) or TSC2 (tuberin) that are components of the mTOR pathway." (PMID 40498018, 2025). "Tuberous sclerosis (TS) is a multi‐system, neurodevelopmental disorder caused by heterozygous mutations in either Tsc1 or Tsc2 genes, two negative regulators of mammalian target of rapamycin (mTOR) activity." (PMID 39192595, 2024). "Additionally, in view of the TSC/MTOR pathway alterations in these tumor types, it appears that a subset is associated with tuberous sclerosis complex." (PMID 39287823, 2024). "Deregulation of mTOR function due to genetic mutations or altered protein expression is involved in brain diseases, particularly developmental neuropsychiatric disorders such as autism, schizophrenia, and tuberous sclerosis." (PMID 35631316, 2022). "In addition, DEGs at week 15 were enriched in genes from the microglia-associated complement system, which has previously been associated with increased mTOR activity in tuberous sclerosis patients’ post-mortem brain material." (PMID 35631316, 2022). "In 2022, FDA registered the recent mTOR inhibitor for clinical use under the name HyftorTM of which rapamycin is an active compound in this substance to treat facial angiofibroma linked with tuberous sclerosis in children over 6 years of age and adults." (PMID 36428613, 2022). "Tuberous sclerosis (TSC) is an autosomal dominant genetic disorder in which mutation of TSC1 or TSC2 genes leads to increased activation of the mammalian target of rapamycin (MTOR) pathway." (PMID 33897576, 2021). "Therefore, we examined several proteins with known involvement in the PI3K/AKT/mTOR signaling pathway, as well as others that are known to be aberrant in animal models of Fragile X syndrome, tuberous sclerosis, and PTEN deficiency." (PMID 27819284, 2016). "mTOR deregulation is observed in multiple sporadic cancer types; however, it also plays a causative role in various familial tumor syndromes such as Cowden syndrome, Peutz-Jeghers syndrome and Tuberous Sclerosis as recently summarized." (PMID 26255626, 2015). "Dysregulated TSC/mTOR signaling may play a pathogenetic role in forms of syndromic autism, such as autism associated with tuberous sclerosis, a genetic disorder caused by heterozygous TSC1 or TSC2 mutations." (PMID 25114803, 2014). "The mTORC2 complex formed by mTOR associated with Rictor is able to phosphorylate and activate Akt, whereas the mTORC1 complex formed by mTOR and Raptor is indirectly activated by Akt, through the phosphorylation of the tuberous sclerosis complex." (PMID 23915343, 2013). "In addition to tuberous sclerosis complex, at least three other neurogenetic disorders have been associated with aberrant activation of mTOR in the brain: neurofibromatosis 1, fragile X syndrome, and PTEN associated conditions." (PMID 24379984, 2013). "They encompass angiomyolipomas, lymphangioleiomyomas, and related tumors, many of which share pathogenic activation of the mammalian target of rapamycin (mTOR) signaling pathway, particularly in association with tuberous sclerosis complex (TSC)." (PMID 41333508, 2025).
tuberous sclerosis (continued). "Aberrant mTOR signaling has been implicated in a range of neurodevelopmental disorders, including tuberous sclerosis complex (TSC) and FCD, underscoring the pathway's importance in maintaining developmental homeostasis." (PMID 40365712, 2025). "Especially in relation to genes associated with the mTOR pathway, considering the approved targeted therapies for tuberous sclerosis, future gene therapies targeting these genes or their pathways could offer new strategies for disease-modifying treatments in mTLE." (PMID 40217352, 2025). "The mTOR pathway is also involved in the pathogenesis of tuberous sclerosis complex (TSC), which results from mutations in the TSC1 (encoding hamartin) or TSC2 (encoding tuberin) gene." (PMID 36197220, 2022). "The other highly ASD-penetrant heterozygous mutations in the TSC1 or TSC2 genes, key regulators of mTOR signaling, cause tuberous sclerosis (TSC)." (PMID 35055151, 2022). "Mutations in mTOR pathway genes can also occur in the germline giving rise to systemic NDDs that affect multiple organ systems, such as in Tuberous Sclerosis Complex (TSC)." (PMID 35058746, 2021). "The mTOR signaling plays vital roles in dendritic formation and axon guidance during normal brain development, and aberrant mTOR signaling has been implicated in neurodevelopment disorders characterized by cognitive deficits, such as tuberous sclerosis and fragile X syndrome." (PMID 33430764, 2021). "We investigated the effect of the mammalian target of rapamycin (mTOR) inhibitor everolimus on tuberous sclerosis complex- (TSC-) associated autistic symptoms and focal seizures with impaired awareness in a female child with TSC." (PMID 31871809, 2019). "Tuberous sclerosis (TSC) is an inherited tumour syndrome caused by mutations in TSC1 or TSC2 that lead to aberrant activation of mTOR." (PMID 28938574, 2017). "Tuberous sclerosis (TSC) is an inherited disease caused by mutations in TSC1 or TSC2 that lead to aberrant activation of mTOR and development of tumours in multiple organs." (PMID 28938574, 2017). "Hyperactive mammalian target of rapamycin (mTOR) is associated with cognitive deficits in several neurological disorders including tuberous sclerosis complex (TSC)." (PMID 24806451, 2014). "Tuberous sclerosis (TSC) related tumors are characterized by constitutively activated mTOR signaling due to mutations in TSC1 or TSC2." (PMID 21915260, 2011). "Mutations in genes such as TSC1, TSC2, and MTOR itself, which lead to hyperactivation of the mTOR pathway, are central to the pathogenesis of diseases like tuberous sclerosis complex (TSC) and certain forms of cancer." (PMID 40358185, 2025). "mTOR inhibitors also play a crucial role in treating the neuropsychiatric symptoms of mTORopathies, such as tuberous sclerosis, by modulating the mTOR pathway, which is dysregulated in these conditions." (PMID 40358185, 2025). "The fetus was clinically diagnosed with tuberous sclerosis, and therapy was initiated with maternally administered sirolimus, an mTOR inhibitor." (PMID 40490815, 2025). "Clinically, SEGAs in the context of tuberous sclerosis complex respond to mTOR inhibition resulting in significant tumor shrinkage and seizure reduction." (PMID 41074169, 2025). "For instance, mutations in TSC1/2 and PTEN lead to hyperactivation of the PI3K-Akt-mTOR pathway, contributing to conditions such as tuberous sclerosis complex and macrocephaly." (PMID 40149774, 2025). "In animal model studies of tuberous sclerosis, inhibition of the mTOR pathway in young animals prevented neurological and behavioral phenotypes." (PMID 40434434, 2025). "A precise diagnostic conclusion also facilitates targeted therapeutic interventions, such as the use of mTOR inhibitors in tuberous sclerosis, streamlines educational and behavioral planning, and provides families with accurate recurrence-risk counselling." (PMID 41462726, 2025).
tuberous sclerosis (continued). "In mouse models of Tuberous Sclerosis Complex (TSC), where mTOR pathway hyperactivation is a hallmark, rapamycin prevented seizures, reduced mortality, and rescued neuropathology (i.e., glial proliferation and disrupted cortical architecture)." (PMID 40620657, 2025). "For example, excessive hippocampal mTOR signaling leads to impairments in learning and memory in an animal model of tuberous sclerosis." (PMID 41002439, 2025). "In individuals with NDDs, early disruptions in protein homeostasis (e.g., mTOR dysregulation in tuberous sclerosis complex) are promising but less validated biomarkers." (PMID 41179085, 2025). "Based on these findings, the International Tuberous Sclerosis Complex Consensus Conference (ITSCCC) recommends the use of an mTOR inhibitor as first-line therapy for asymptomatic or growing AMLs larger than 3 cm." (PMID 40861726, 2025). "The mammalian target of rapamycin (mTOR) signaling pathway plays a central role in the pathophysiology of tuberous sclerosis complex (TSC), particularly in the regulation of aberrant cell growth and tumorigenesis." (PMID 40722560, 2025). "Tuberous sclerosis 2 is the basic inhibitor of the mechanistic target of rapamycin (mTOR) signaling pathway that can modulate apoptosis." (PMID 40028035, 2025). "Specifically, Akt, a downstream regulator of PI3K, directly phosphorylates and activates mTOR, and it can also indirectly activate mTOR by inactivating the tuberous sclerosis complex TORC2, which inhibits mTOR." (PMID 41294817, 2025). "Tuberous sclerosis complex (TSC) is a neurodevelopmental disorder that results in hyperactive mammalian/mechanistic target of rapamycin (mTOR) signaling leading to altered neuronal excitability and seizures; however, the underlying mechanisms remain a mystery." (PMID 39253727, 2024). "Tuberous sclerosis is mainly caused by TSC1 or TSC2 gene mutation, which leads to a series of clinical manifestations such as enhanced mTOR pathway activity and seizures." (PMID 39539663, 2024). "The Tuberous Sclerosis Complex, caused by mutations in the TSC1 or TCS2 genes, results in abnormalities in cell growth and differentiation through disruption of the mTOR (mammalian target of rapamycin) pathway." (PMID 39781307, 2024). "Tuberous sclerosis is another AD “tumor syndrome,” caused by pathogenic variants in the TSC1 or TSC2 tumor suppressor genes, tuberin and hamartin, that inhibit the mammalian target of rapamycin (mTOR) pathway." (PMID 37644229, 2024). "Tuberous Sclerosis Complex (TSC) is a lynchpin disorder, as it results in overactive mammalian target of rapamycin (mTOR) signaling, which has been implicated in a multitude of disease states." (PMID 39253727, 2024). "The potential for mTOR inhibition in preventing epileptogenesis, particularly in the context of tuberous sclerosis and other common acquired epilepsies, is a significant area of research." (PMID 39867454, 2024). "Hyperactivation of the mTOR pathway, as seen in conditions like tuberous sclerosis, leads to abnormal LTP in the hippocampal area CA1." (PMID 39867454, 2024). "Even in cases unrelated to tuberous sclerosis complex, activation of the mTOR pathway has been observed in some PEComas." (PMID 39220642, 2024). "The clinical impact of mTOR inhibitors has been profound, contributing to the treatment of a wide range of human diseases, including cancers, tuberous sclerosis complex (TSC), and Alzheimer’s disease." (PMID 39770519, 2024). "These drugs inhibit mTOR signaling and may provide some benefit in specific PEComas, particularly those associated with tuberous sclerosis complex (TSC) or showing activation of the mTOR pathway." (PMID 39220642, 2024). "Dysregulation of the mTOR pathway is observed in various human central nervous system diseases, including tuberous sclerosis complex, autism spectrum disorder (ASD), and neurodegenerative diseases, including Parkinson’s disease and Huntington’s disease." (PMID 39280263, 2024).
tuberous sclerosis (continued). "WNT signaling has been identified as an upstream regulator of mammalian target of rapamycin (mTOR) signaling, promoting mTORC1 activity by preventing induction of the tuberous sclerosis complex." (PMID 37152076, 2023). "However, EVT has prominent or extreme cytoplasmic vacuolation whereas in mTOR-mutated eosinophilic RCCs, we observed large cells with perinuclear cytoplasmic shrinkage resembling the so-called spider cells of cardiac rhabdomyomas occurring, interestingly, in tuberous sclerosis patients." (PMID 37938323, 2023). "Since the beginning of the national program for tuberous sclerosis patients in Romania in 2014, 21 out of the 32 patients in our group opted for the mTOR inhibitor treatment and met the inclusion criteria." (PMID 37892688, 2023). "Subependymal giant cell tumors are well-known manifestations of tuberous sclerosis caused by alterations in TSC1 or TSC2, and the pathogenic activation of mTOR leads to tumor development." (PMID 37221626, 2023). "mTOR has demonstrated good clinical efficacy as a therapeutic target for CNS diseases in neurodevelopmental disorders such as tuberous sclerosis." (PMID 37098609, 2023). "Tuberous sclerosis complex results from inactivating mutations in the TSC1 or TSC2 genes, resulting in hyperactivation of the mTOR signaling pathway, which regulates cell growth, proliferation, survival, and autophagy." (PMID 37232723, 2023). "In the brain, mTOR signaling has been shown to be a major regulator of synaptic function, and its inhibition has been shown to rescue synaptic phenotypes in tuberous sclerosis." (PMID 36139380, 2022). "Bourneville mutations cause tuberous sclerosis syndrome in the TSC protein TSC2, which suppresses mTOR action under hypoxic and energy-depleted circumstances." (PMID 36428613, 2022). "It is well known that functional mutations of tuberous sclerosis complex 1(TSC-1), a negative regulator of mTOR, can cause TSC, and the affected patients may require organ transplantation after organ failure." (PMID 36186130, 2022). "Intriguingly, chordoma sometimes occurs in patients with tuberous sclerosis complex, which is characterized by loss of the mTOR negative regulators TSC1/2, further hinting at a role for the PI3K/mTOR pathway in chordoma pathogenesis." (PMID 36387127, 2022). "Protein kinase B (Akt) is also activated by PI3K activation, and Akt then activates mTOR by phosphorylating and deactivating the tuberous sclerosis complex." (PMID 36699066, 2022). "In animal models of tuberous sclerosis complex, mTOR inhibitors were shown to have antiepileptogenic activity." (PMID 36145334, 2022). "mTOR signaling has a well-established role in hamartoma syndromes such as tuberous sclerosis complex (TSC) and other mTORopathies." (PMID 36226315, 2022). "mTOR inhibitors are used as a maintenance treatment to control subependymal giant cell astrocytoma (SEGA) tumors in tuberous sclerosis." (PMID 35877430, 2022). "Neuronal mTOR overactivity is related to changes in seizure severity and related neuropathology in the tuberous sclerosis complex (TSC) and focal cortical dysplasia (FCD)." (PMID 34832914, 2021). "Wong M. Mammalian target of rapamycin (mTOR) inhibition as a potential antiepileptogenic therapy: From tuberous sclerosis to common acquired epilepsies." (PMID 34901706, 2021). "The ESES findings improved by additional treatment with sirolimus (an mTOR inhibitor), which has been shown to be effective for treatment-resistant seizures in patients with tuberous sclerosis." (PMID 34208064, 2021). "Topical rapamycin improved hypopigmented macules in patients with tuberous sclerosis, who showed mTOR activation." (PMID 33924406, 2021). "Recent reports have suggested that mTOR inhibitor sirolimus and related drugs show some benefit in non-tuberous sclerosis complex PEComas." (PMID 34123648, 2021).
tuberous sclerosis (continued). "In tuberous sclerosis, heterozygous variants in TSC1 or TSC2 (mTOR pathway genes) cause a multisystem disorder including epilepsy, developmental delay and propensity to non-malignant overgrowth such as cortical tubers." (PMID 34713254, 2021). "Mutations in proteins belonging to PI3K-AKT-mTOR pathway lead to various syndromes (“mTORopathies”) including Bannayan-Riley-Ruvalcaba syndrome (BRRS), tuberous sclerosis, Peutz-Jeghers syndrome characterized by hyperactivation of mTOR-signaling." (PMID 34485194, 2021). "Concordantly several clinical trials of the use of mTOR inhibitor–everolimus in patients with tuberous sclerosis were performed, yielding positive results and leading to registration of everolimus to treat high-risk renal AMLs." (PMID 34442003, 2021). "For instance, everolimus, an inhibitor of mTOR which is used for treatment of tumor manifestations in patients with tuberous sclerosis complex also provide impressive therapeutic effect on improving neuropsychiatric symptoms." (PMID 34512273, 2021). "The importance of the mTOR pathway in NET biology was first suggested by the appearance of pancreatic NETs in patients with tuberous sclerosis, which is caused by naturally occurring alleles of TSC1 or TSC2 that are known to activate mTOR." (PMID 34680217, 2021). "On the other hand, over-activation of mTOR complexes leads to a neurodevelopmental disorder, such as tuberous sclerosis (TS) and several neurodegenerative diseases, including Alzheimer’s, Parkinson’s, and Huntington’s diseases." (PMID 33670176, 2021). "Overactivation of mTOR has been involved in cognitive deficits observed in preclinical models of neurodevelopmental disorders, such as tuberous sclerosis, Fragile X syndrome and schizophrenia." (PMID 34576341, 2021). "Increased AKT/mTOR activity is consistent with deficiencies of FMR1, TSC1/2, or PTEN found in Fragile X, tuberous sclerosis, and Cowden syndrome." (PMID 33482199, 2021). "Several mTOR inhibitors are currently FDA-approved for the treatment of tuberous sclerosis complex and to prevent lung function decline in patients with lymphangioleiomyomatosis." (PMID 34138757, 2021). "Tuberous sclerosis, for example, is a multisystem disorder resulting from mutations in either the TSC1 or TSC2 genes, leading to abnormal signalling in the mammalian target of rapamycin (mTOR) pathway." (PMID 33340339, 2021). "Upregulation of mTOR signaling due the inactivation of TSC1/2 (Tuberous Sclerosis 1 and 2) is believed to be a key oncogenic driver in this disease." (PMID 33180365, 2020). "This is based on an assumption that tuberous sclerosis (TS) is the most frequent syndromic presentation of cardiac tumors, and mTOR inhibitors are effective in treating CNS and kidney neoplasms of TS." (PMID 32964316, 2020). "Inhibition of mTOR is effective in the context of tuberous sclerosis, another neurocutaneous disease, prompting investigation of pharmacological inhibition of the mTOR pathway for NF1." (PMID 32439933, 2020). "According to the International Tuberous Sclerosis Complex Consensus Conference 2012, mTOR inhibitors have been recommended as a first-line treatment to reduce the size of renal AMLs associated with TSC." (PMID 33219488, 2020). "In tuberous sclerosis patients, everolimus was capable of controlling refractory epilepsy and alleviating autistic symptoms by inhibiting the mTOR pathway activity." (PMID 30881383, 2019). "The overactivation of mTOR has been implicated in the pathogenesis of syndromic autism spectrum disorder (ASD), such as tuberous sclerosis complex (TSC)." (PMID 30621732, 2019). "The increased mTOR pathway activity is a central pathogenic mechanism shared by FXS, aging, and several other neurological disorders such as autism and tuberous sclerosis, evidenced by reproducible results from yeast to mammalian animal models." (PMID 30881383, 2019).